ITGB3 (integrin subunit beta 3)
Diseases named in the same sentence as ITGB3 in open-access papers (continued):
Sharing a sentence is not in itself a finding about the gene and the disease.
Thrombocytopenia (16 papers, 2014 to 2025). A reduction in the number of circulating thrombocytes. "Previously reported ITGA2B and ITGB3 variants related to thrombocytopenia were clustered in a confined region of the membrane-proximal cytoplasmic domains, the inner membrane clasp." (PMID 33276370, 2020). "Among these, GP1BA (c.1591dup, c.1525C>T, and c.378C>G), ITGB3 (c.1394C>G), NBEAL2 (c.3796del), WAS (c.655G>T, deletions of exons 1-2), and MPL (c1511T>A) were notable for their association with severe thrombocytopenia and morphological platelet abnormalities." (PMID 40488176, 2025). "These cases have deserved the designation of GT-like syndrome (GTLS) or ITGA2B/ITGB3-related thrombocytopenia (ITGA2B/ITGB3-RT)." (PMID 33276370, 2020). "In the LCMV-infected mouse model for thrombocytopenia, ITGB3−/− mice developed a severe hemorrhagic anemia after infection, even with normal platelet counts, suggesting a key role of ITGB3 in protecting against bleeding." (PMID 24921924, 2014). "In addition, deficiency or reduction of the major platelet membrane GPIb-IX and GPIIb/IIIa also cause macrothrombocytopenia named Bernard–Soulier syndrome (BSS) and ITGA2B/ITGB3-related thrombocytopenia, respectively." (PMID 34657146, 2021). "Rare pathogenic variants in either the ITGA2B or ITGB3 genes have been linked to autosomal dominant macrothrombocytopenia associated with abnormal platelet production and function, deserving the designation of Glanzmann Thrombasthenia-Like Syndrome (GTLS) or ITGA2B/ITGB3-related thrombocytopenia." (PMID 33276370, 2020). "We found eight proteins (ITGA2B, ITGB3, VWF, PLEK, TNF, TLR2, BCL2 and BCL2L1) were the core targets of DMAG for the treatment of thrombocytopenia." (PMID 34837956, 2021). "Genetic defects identified in the different families with thrombocytopenia, affecting the ITGA2B or the ITGB3 genes." (PMID 33276370, 2020). "The lower integrin α2b and β3 (ITGA2B, ITGB3) protein levels found in the MLL-r samples is consistent with the presumed BM microenvironment origin of these proteins: they would be expected to be present at lower levels in the BM of leukemia cases, which typically present with thrombocytopenia." (PMID 34646384, 2021).
gastric cancer (15 papers, 2016 to 2024). A primary or metastatic malignant neoplasm involving the stomach. "As to ITGB3, it was reported to promote metastasis of colorectal cancer, nasopharyngeal carcinoma, pancreatic cancer, and gastric cancer." (PMID 38814534, 2024). "ITGB3 is upregulated by sponging miR-124-3p, consequently enhancing the proliferation, migration, and invasion of the cells in gastric cancer." (PMID 37760946, 2023). "As for miR-124-3p, it has been illustrated to suppress cell migration in gastric cancer via targeting ITGB3." (PMID 35761386, 2022). "We revealed miR-124-3p can bound to partial complementary sites of ITGB3 mRNA and induce post-transcriptional silencing of the ITGB3 gene to inhibit gastric cancer cell proliferation and invasion." (PMID 34715856, 2021). "In conclusion, our collective findings demonstrated that the lncRNA HOXA11-AS can activate ITGB3 expression to promote the migration and invasion of gastric cancer by sponging miR-124-3p." (PMID 34715856, 2021). "We demonstrated that lncRNA HOXA11-AS can increase ITGB3 expression to promote the migration and invasion of gastric cancer by sponging miR-124-3p." (PMID 34715856, 2021). "Previous studies demonstrated that miRNA-124-3p (miR-124-3p) can down-regulate ITGB3 expression and inhibit gastric cancer cell proliferation and migration." (PMID 34715856, 2021). "Inhibiting the expression of ITGB3 can increase the expression of miR-124-3p and thus inhibit the migration and invasion of gastric cancer, suggesting that miR-124-3p and ITGB3 may also be promising therapeutic targets for gastric cancer." (PMID 33550277, 2021). "miR-124-3p can inhibit integrin β3 (ITGB3) expression to suppress the migration and invasion of gastric cancer (GC), and in the process lncRNA HOXA11-AS may act as a molecular sponge." (PMID 34715856, 2021). "In order to further explore the relation between lncRNA HOXA11-AS and miR-124-3p as well as ITGB3, we conducted lncRNA HOXA11-AS overexpression experiments, silencing experiments and rescue experiments in gastric cancer cell lines." (PMID 34715856, 2021). "Firstly, we detected the basal levels of HOXA11-AS and ITGB3 in normal gastric mucosal epithelial cells GES-1, as well as gastric cancer cells MNK45, AGS and MGC803." (PMID 34715856, 2021). "ITGB3 and ZEB1 were found to be targeted by miR-124-3p in promoting gastric cancer proliferation and invasion." (PMID 33482814, 2021). "Because previous studies coupled ITGB3 to EMT and metastasis, and silencing of ITGB3 by a variety of approach has been demonstrated to rescue from metastasis formation in several cancer models, our study suggest that targeting this integrin could be useful in the treatment of gastric cancer." (PMID 27409173, 2016).
lung carcinoma (14 papers, 2013 to 2026). "The decrease in ITGA2B and ITGB3 levels in platelets during this prothrombotic condition of patients with lung cancer and LA with thrombosis history may be caused by the continuous shedding of extracellular vesicles, which was recently also described as “membrane pearling” of platelet pseudopodia." (PMID 34066760, 2021). "Collectively, these findings identify exosomal L1CAM as a key regulator of brain-specific metastasis and support the clinical utility of the L1CAM/ITGB3 panel as a noninvasive biomarker for BrM in lung cancer." (PMID 41675572, 2026). "ITGB3 K416 acetylation intensity was significantly higher in cancer tissue samples than that in normal tissue samples obtained from lung cancer patients." (PMID 36453571, 2023). "Dramatically elevated serum SIRT2 level in lung cancer patients especially these highly metastatic SCLC patients strongly correlated with deacetylation of ITGB3 vWA domain‐K416 as well as other extracellular proteins of cancer cells." (PMID 36453571, 2023). "Collectively, SIRT2 proteins secreted from macrophages were responsible for ITGB3 aK416 deacetylation of lung cancer cells." (PMID 36453571, 2023). "The abundance of both integrins of the fibrinogen receptor integrin αIIbβ3, ITGA2B and ITGB3, were significantly reduced in platelets of patients with lung cancer." (PMID 34066760, 2021). "Therefore, a close connection between SIRT2 secretion from macrophages and ITGB3 vWA domain (K416) deacetylation in the tumor microenvironment of human lung cancer patients has been established." (PMID 36453571, 2023). "Also, miR-483-3p could reverse EMT to MET phenotype by targeting ITGB3 gene and thereby inhibiting downstream FAK/ERK pathways which causes reduction in lung cancer cell migration and metastasis." (PMID 38372877, 2024). "Notably, immunofluorescent staining detected SIRT2 proteins either barely overlay with ITGB3‐aK416 positive lung cancer cells or sporadically overlay with CD68 positive macrophages, indicating SIRT2 proteins visualized here were mainly distributed in the extracellular space." (PMID 36453571, 2023). "Compared with those in PC9 lung cancer cells, the mRNA expression of PLAT, ITGB3, TNC, AKT, FAK and PI3K were upregulated in PC9GR." (PMID 39754146, 2025). "The abundance of TLN1, TUBA4A, HSPA8, ITGB3, TSG101, and PACSIN2 in the plasma of lung cancer patients was measured using targeted mass spectrometry and compared to that in plasma from healthy volunteers." (PMID 34684727, 2021). "MiR-98-5p was significantly increased and promoted cell proliferation and invasion in lung cancer by directly targeting TWIST, PAK1, and ITGB3." (PMID 29970191, 2018). "CXCL12 was shown to increase the migration of lung cancer cells through the CXCR4-mediated activation of ERK, which in turn activates IKKa/b and NF-κB, resulting in the activations of integrins (ITGB1 and ITGB3)." (PMID 23322021, 2013). "Together, these observations suggest that FN1, TLN1, ITGB3, HSPA8, and TUBA4A detection in the blood using SRM/SIS may serve as an indicator of tumors, and elevations in their concentrations coupled with PACSIN2 detection discriminate lung cancer from other malignancies." (PMID 34684727, 2021).
myocardial infarction (14 papers, 2014 to 2024). Gross necrosis of the myocardium, as a result of interruption of the blood supply to the area, as in coronary thrombosis. "For example, the rs5918 variant, located in the ITGB3 gene (chr17:45360730), reduces the efficacy of aspirin and clopidogrel (indicated for coronary artery disease and myocardial infarction) and it shows a higher allele frequency in IBS and TSI than in Roma." (PMID 34220960, 2021). "Itgb3 (Integrin Subunit Beta 3) is related to myocardial infarction risk." (PMID 34130651, 2021).
atherosclerosis (11 papers, 2014 to 2024). A disease characterized by the build-up of fatty material and calcium deposition in the arterial wall resulting in partial or complete occlusion of the arterial lumen. "Studies have shown that ITGB3 deficiency can promote atherosclerosis and pulmonary inflammation in high-fat-fed and hyperlipidemic mice." (PMID 36180828, 2022). "Overall, loss of ITGB3, which encodes integrin β3, exacerbates atherosclerosis in high-fat diet-fed ApoE (−/−) mice." (PMID 36180828, 2022). "Integrins are heterodimeric receptors that link the extracellular matrix to the cytoskeleton, and deletion of the gene encoding integrin β3 (Itgb3) exacerbates atherosclerosis burden in atheroprone mice." (PMID 29802249, 2018). "Integrins are heterodimeric transmembrane proteins, composed of α and β subunits, that link the extracellular matrix to the cytoskeleton, and global deletion of Itgb3 (encoding integrin β3) exacerbates atherosclerosis in high fat-fed ApoE(−/−) mice." (PMID 29802249, 2018). "ITGB3 encodes the integrin β3-subunit, a protein involved in platelet aggregation and endothelial function, processes that are crucial in the development of atherosclerosis." (PMID 39028281, 2024). "In sum, the increased number of recruited SMC progenitors and altered fate of these cells in Itgb3 mutant mice are likely major factors exacerbating atherosclerosis." (PMID 29802249, 2018). "This study only validated ITGB3 as a target of miR-351-5p, but it remains to be studied whether miR-351 can also regulate other targets involved in the regulation of atherosclerosis." (PMID 36180828, 2022). "In mice, knockout of the ITGB3 gene exacerbates atherosclerosis of the aorta." (PMID 34418970, 2021). "Later detection should be added in patients with only atherosclerosis without diabetes to determine whether the mir-351/ITGB3/PIK3R1/Akt pathway is also affected." (PMID 36180828, 2022).
leukemia (11 papers, 2012 to 2023). A malignant (clonal) hematologic disorder, involving hematopoietic stem cells and characterized by the presence of primitive or atypical myeloid or lymphoid cells in the bone marrow and the blood. "This leukemia variant depends on Wnt-β-catenin; the negative β-catenin regulator Apc is decreased and at the same time this leukemia is also characterized by high expression of ITGB3 as well as β-catenin (Ctnnb1) and High mobility group box 3 (Hmgb3)." (PMID 29342970, 2018). "Herein we show that in leukemia cells ERG overexpression promotes a mesenchymal-like gene expression signature that includes: CD24, CD44, ITGA10, ITGB5, ITGB3, ITGA2B and the morphogenic-associated genes, such as SHANK3, TYROBP." (PMID 24504051, 2014). "ITGB3 is an essential molecule for leukaemia cell propagation." (PMID 29340063, 2017). "The categories overlap: for example, amongst the adhesion related genes, ITGB3 and CD44 are also essential for the maintenance of leukaemia initiating cells." (PMID 29340063, 2017). "ITGB1, ITGB3, ITGA4, and ITGA5 were expressed in five of the six leukemia cell lines, and ITGB4 and ITGA6 were specifically expressed in the three EVI1high leukemia cell lines." (PMID 22295105, 2012). "Two days after treatment, the binding activity of all four cell lines was significantly reduced by the treatment with anti-ITGA6 or anti-ITGB4 antibodies; however, isotype IgG, anti-ITGB2 or anti-ITGB3 antibodies did not inhibit the binding of EVI1high leukemia cells to matrigel." (PMID 22295105, 2012). "Several genes upregulated in the TF1a dormancy model have been described in leukaemia initiating cells, but appear not to be crucial for maintenance of normal HSCs, e.g. CD44, ITGB3, TIM3 (HAVCR2) and IL3RA." (PMID 29340063, 2017). "Two leukemia (UCSD/AML1 and MOLM1) and two primary human AML (PT9 and PT11) cells lines were cultured on matrigel and treated with or without anti-ITGA6, ITGB2, ITGB3, or ITGB4 antibodies." (PMID 22295105, 2012).
nasopharyngeal carcinoma (11 papers, 2020 to 2025). A carcinoma arising from the nasopharyngeal epithelium. "lncRNA FAM225A has been shown to act as a ceRNA absorbing miR-1275, up-regulating ITGB3 and promoting metastasis in nasopharyngeal carcinoma." (PMID 34118875, 2021). "LncRNA FAM225A could expedite cell migration of nasopharyngeal carcinoma through playing as a ceRNA to regulate miR-590-3p/miR-1275/ITGB3 axis." (PMID 35761386, 2022). "EVs released from platelets in nasopharyngeal carcinoma patients can increase integrin β3 (ITGB3) expression in NPC cells." (PMID 40328736, 2025). "For example, lncRNA FAM225A facilitates nasopharyngeal carcinoma (NPC) tumor formation and metastasis by sponging miR-590-3p/miR-1275 as a ceRNA and increasing ITGB3 expression." (PMID 33614632, 2020). "In patients with nasopharyngeal carcinoma (NPC), PEVs can be transferred into NPC cells and upregulate the expression of integrin β3 (ITGB3)." (PMID 39183323, 2024). "In nasopharyngeal cancer, lncRNA FAM225A promoted NPC cell proliferation, migration and invasion by competitively absorbing miR-590-3p and miR-1275 to upregulate ITGB3." (PMID 32209098, 2020).
pancreatic cancer (11 papers, 2019 to 2026). "ICAM-1 and ITGB3 were found to be positively associated with CMG2 expression in pancreatic cancer cell lines at both the transcript and protein levels." (PMID 39199664, 2024). "In the present study, the upregulation of ITGB3 mediated by CMG2 was also observed in the pancreatic cancer cells." (PMID 39199664, 2024). "Among them, TPT1-AS1 acts as an endogenous sponge of miR-30a-5p, increasing the levels of integrin β 3 (ITGB3) in pancreatic cancer cells." (PMID 36522691, 2022). "Although previous data reported that H19 overexpression reduced ITGB3, ITGB5, and ITGA5 in bladder cancer cells and increased ITGB1 and ITGA1 in pancreatic cancer cells, the molecular mechanism by which H19 regulates integrin was not elucidated." (PMID 31426484, 2019). "Analysis using the Xiantao online tools revealed that the CD274 (PD-L1) gene exhibits high expression levels in tumor samples from hepatocellular carcinoma, pancreatic cancer, renal cancer, and urothelial cancer, alongside elevated expression of αv (ITGAV) and β3 (ITGB3) genes." (PMID 41601637, 2026). "ITGB3 was identified not only in EVs isolated from brain-tropic MDA231-BrM2 cells, but also in EVs from liver-tropic and lung-tropic BC cells, as well as EVs from liver-tropic and lung-tropic colorectal, gastric, and pancreatic cancer cells." (PMID 40662366, 2025). "To investigate whether cytokines and cellular stress stimulate ITGB3 expression in a STAT3-dependent manner, we developed STAT3 CRISPR knockout (KO) clones in FG pancreatic cancer cells." (PMID 40701148, 2025). "In this study, we investigated the synergistic effects of juglone and selenium on PANC-1 and BxPC-3 pancreatic cancer cell lines by cell adhesion and invasion assays and evaluation of the mRNA and protein expressions of CDH1, ITGB3 and COL4A3 which play role in metastasis and angiogenesis processes." (PMID 36407358, 2022).
Sepsis (11 papers, 2014 to 2025). Sepsis is defined as life-threatening organ dysfunction caused by a dysregulated host response to infection. "We have previously identified CMTM5 and ITGB3 as associates of the hub entity MYL9; key differentiators of Sepsis and SIRS with platelet activation function." (PMID 38332914, 2023). "Expression of sepsis-specific biomarkers PLXNB3, ITGB3, CETP, CMTM5 and PF4 correlated positively with each other at the Day1 time point and to a slightly lesser degree with MIA and CRP." (PMID 38332914, 2023). "Gene entities shared between sepsis and severe sepsis response hubs are; TDRD9 – LIN7A, GPR84 – ENTPD7, PYCT1A and ZDHHC19, CD177 – DDAH2 and RGL4, SLC16A3 – DENND3 and MBD6, MYL9 – CMTM5, ITGB3, ITGA2B, NRGN, SELP and TREML1." (PMID 32318053, 2020). "ITGB3 (integrin subunit beta 3) and ITGA2B (integrin subunit alpha 2 beta; both component chains of the heteromeric, platelet-specific integrin αIIbβ3), have also been the focus of intense interest in sepsis." (PMID 32318053, 2020). "In GSE9960, CMTM5+ITGB3+PLA2G7-GPR124-ARHGEF10L performed best when comparing healthy controls and sepsis caused by mixed infection or gram-positive infection with reduced performance for sepsis caused by gram-negative infections." (PMID 38332914, 2023).
colorectal cancer (10 papers, 2016 to 2025). A primary or metastatic malignant neoplasm that affects the colon or rectum. "Further on, all three GPBAR1 ligands were effective in inducing the expression of ITGB3, a integrin beta-chain subunit coded by a serotonin-related gene on chromosome 17, that has been reported to be associated with the risk of several human cancers, including colorectal cancer." (PMID 27409173, 2016). "In the regulatory effect of lipocalin 2, ITGB3 conferred resistance to 5-fluorouracil in colorectal cancer." (PMID 38814534, 2024). "As previously reported, miR−30a−5p inhibits migration, invasion, and EMT processes by downregulating ITGB3 in colorectal cancer." (PMID 36555361, 2022). "MiR-30a-5p is downregulated in colorectal cancer and can suppress tumor metastasis by targeting integrin ß3 (ITGB3), which is overexpressed in colorectal cancer." (PMID 33291485, 2020). "Furthermore, ROS-induced migration and invasive ability of colorectal cancer cells were significantly altered by downregulating or upregulating ITGB3 expression." (PMID 39721996, 2024). "In colorectal cancer, the molecule network IGF1-HOXA13-ACLY/IGF1R and CXCL12-HOXB5-CXCR4/ITGB3, targeted blocking the downstream protein with small molecular compounds serves as a promising anticancer therapy." (PMID 34722321, 2021).
dengue (10 papers, 2010 to 2025). "In a matched case–control study conducted in Brazil, the association between MBL2, CLEC5A, ITGB3 and CCR5 genes and dengue severity was investigated in children." (PMID 33766078, 2021). "Furthermore, the FCPLJ treatment has also downregulated the genes associated with the endothelial cell biology (ITGB3, ICAM1 and FN1) that are involved in the endothelial permeability process during dengue virus infection." (PMID 33919457, 2021). "The FCPLJ treatment has affected the regulation of four genes, CCL-2/MCP-1 (upregulated), ITGB3, ICAM1 and FN1 (downregulated), which were involved in endothelial permeability regulation during dengue virus infections." (PMID 30944031, 2019). "The FCPLJ treatment downregulated ITGB3, ICAM1 and FN1 genes, which were upregulated during dengue virus infection." (PMID 30944031, 2019).